LRRC71 (leucine rich repeat containing 71)
Synonyms: C1orf92; FLJ32884
Tractability: No criterion of Open Targets' tractability assessment is met for any kind of drug.
Gene: Protein-coding gene on chromosome 1 (156,920,631 to 156,933,094, forward strand). Ensembl gene ENSG00000160838.
Genetic constraint (gnomAD): Loss-of-function variants: 56 observed, 64.38 expected, observed/expected ratio (o/e) 0.87, 90% interval 0.7 to 1.09. The upper end of that interval is the gene's LOEUF score, 1.09, which puts it in group 4 of 6, group 1 being the genes least tolerant of losing a copy. Missense variants: 721 observed, 669.01 expected, observed/expected ratio (o/e) 1.08, 90% interval 1.01 to 1.15. Synonymous variants: 321 observed, 281.81 expected, observed/expected ratio (o/e) 1.14, 90% interval 1.04 to 1.25.
Homologues: Orthologues: chimpanzee LRRC71 (99% identical), macaque LRRC71 (98% identical), pig LRRC71 (87% identical), rabbit LRRC71 (86% identical), dog LRRC71 (84% identical), rat Lrrc71 (83% identical), mouse Lrrc71 (81% identical), guinea pig LRRC71 (78% identical), tropical clawed frog lrrc71 (44% identical), zebrafish lrrc71 (35% identical).
Diseases named in the same sentence as LRRC71 in open-access papers:
LRRC71 is named in the same sentence as 4 diseases in open-access papers, as found by Europe PMC text mining. Sharing a sentence is not in itself a finding about the gene and the disease. The quoted sentences say what the papers report.
asthenozoospermia (1 paper, 2026). "LRRC71 represents a potential target for the diagnosis and treatment of male infertility associated with asthenozoospermia." (PMID 42167576, 2026). "Lrrc71 knockout (KO) mice exhibit asthenozoospermia and disrupted mitochondrial sheaths in sperm." (PMID 42167576, 2026).
viral infection (1 paper, 2024). "LRRC71 may also modulate cell proliferation and apoptosis to inhibit viral infection." (PMID 39051372, 2024).
LRRC71 also shares sentences with these, for which no sentence is quoted: glioma (2 papers); male infertility (1).